TLR2 (toll like receptor 2)
Diseases named in the same sentence as TLR2 in open-access papers (continued):
Sharing a sentence is not in itself a finding about the gene and the disease.
tumor (continued). "Additionally, the investigators suggest that activation of TLR2 only induced the cytolytic activity of peripheral and tumor-infiltrating CD8+ T cells." (PMID 36982898, 2023). "The mechanism may be through activation of Amuc, an outer membrane protein of toll-like receptor 2 (TLR2) signaling, resulting in effective tumor regression." (PMID 37035188, 2023). "Once activated, TLR2 signaling promotes tumor growth and survival." (PMID 38203626, 2023). "Then we also evaluated the anti-tumor property of PepO in TLR2−/− and TLR4−/− mice." (PMID 37925462, 2023). "CXCL10, CXCL5, MMP1, CXCL12, CXCL11, CXCL2, STAT1, IL‐6 and TLR2 were hub genes, which may drive the homing of immune cells in tumours and promote immune cell differentiation." (PMID 36524848, 2023). "The use of MMG-11 could provide promising data in cases where RT activation of TLR2 promotes tumor progression and/or metastasis." (PMID 37112730, 2023). "Secretin tumour cell line 1 enteroendocrine cells were treated for 24 or 48 h with toll-like receptor agonists (toll-like receptor 4 selective lipopolysaccharide; toll-like receptor 2 selective Pam3CysSerLys4) and the free fatty acid receptor 2/3 agonists butyrate, propionate and acetate." (PMID 37953845, 2023). "And PANX1, PPIA and TLR2 were highly expressed in tumor group." (PMID 37259066, 2023). "Moreover, the expression of DCN and TLR2 was decreased in CRC tissue compared with their adjacent non-tumor tissue, and the abundance of B.adolescentis was positively correlated with the expression of TLR2 and DCN in CRC tissue." (PMID 37464382, 2023). "Tumor-derived sEVs increase macrophage glycolysis through TLR2-NF-kB signaling to make them obtain immunosuppressive phenotype, which was distinguished by abundant (programmed cell death ligand-1) PD-L1 expression and PD-L1 was positively relevant with levels of GLUT-1 from primary tumors." (PMID 37208722, 2023). "This increased tumor burden in TLR2−/− mice was further explained by the overactivation of signal transducer and activator of transcription 3 (STAT3) in epithelial cells and the elevated expression of tumor-promoting cytokines, such as IL-6, IL-17A and TNF-α in the gut mucosa." (PMID 37519301, 2023). "Thus, the role of TLR2 in anticancer immune responses remains controversial and largely reliant on tumor types and models." (PMID 38203626, 2023). "In summary, our study demonstrated that PepO, as a high level of biosafe immunomodulatory molecule, switches TAM from the tumor-promoting M2 to tumor-inhibitory M1 phenotype by interacting with TLR2 and TLR4 and activating PI3K-AKT-mTOR and inhibiting JAK2-STAT3 pathway." (PMID 37925462, 2023). "However, as discussed in the next section, TLR2 also contributes to tumor progression in a tumor cell-extrinsic manner, by shaping an immunosuppressive TME." (PMID 38203626, 2023). "Conversely, versican secreted by THP-1 cells can ligate TLR-2 on these cells to induce the production of inflammatory cytokines in an autocrine fashion which generates an inflammatory microenvironment congenial for tumor progression." (PMID 37784035, 2023). "Moreover, IHC staining of HPSCC samples from cohort 1 and cohort 2 indicated that the protein levels of TLR2 were reduced in tumor tissues when the expression of ALKBH5 was increased." (PMID 37612282, 2023). "The number of clinical trials with sole TLR2 agonism in tumor immunotherapy is limited." (PMID 36479129, 2022). "The activation of TLR2 signaling in MDSCs induces tumor regression." (PMID 36389785, 2022).
tumor (continued). "In murine models of hepatocellular carcinoma, TLR2-deficient mice showed a decrease in the expression of IFN-γ, TNF-α, (IL)-1α/β, IL-6, and Cxcl-2, which attenuate p21- and p16/pRb-dependent senescence, leading to the increased proliferation of tumor cells." (PMID 35309296, 2022). "In addition, TLR2 synthesis can be stimulated by bacterial lipopolysaccharides (LPS), zymosan from yeast cell wall, and murine or human adipocyte tumour growth factor." (PMID 34854223, 2022). "In addition, a synthetic bacterial lipoprotein (a TLR1/TLR2 agonist) was reported to reduce the suppressive function of Foxp3+ Treg cells and enhance the cytotoxicity of tumor-specific CTL." (PMID 35309296, 2022). "However, our data argue against this and highlight that increased proinflammatory SASP expression (via Tlr2 activation) in early lung tumors can impair tumor progression." (PMID 36351380, 2022). "We therefore sought to determine whether cell-extrinsic mechanisms such as SASP expression contribute to the tumor suppressor effect of Tlr2." (PMID 36351380, 2022). "TLR2 was significantly expressed in most tumor types, except BRCA, LIHC, LUAD, LUSC, and PRAD." (PMID 35937402, 2022). "Our report demonstrates that TLR2 has a tumor suppressor function in NSCLC." (PMID 36351380, 2022). "We observed no significant increase in γδ T cells in Tlr2−/− tumor-bearing lungs, suggesting that the tumor-promoting effect of Tlr2 loss is not mediated via γδ T cell expansion." (PMID 36351380, 2022). "Mechanistically, this molecule binds to TLR2, causes release of Ca2+ and activation of p38, AKT, and NF-κB, thereby polarizing tumor-associated macrophages from a tumor-promoting M2 phenotype into a tumor-killing M1 phenotype." (PMID 35711557, 2022). "TLR2 also induces the anti-tumor M1-like macrophage polarization." (PMID 36479129, 2022). "The SASP regulates non-cell autonomous anti-tumor responses, such as immune surveillance of premalignant cells, and we observe impaired myeloid cell recruitment to lung tumors after Tlr2 loss." (PMID 36351380, 2022). "Other innate immune receptors, such as TLR1 and TLR2 are also reportedly associated with cellular senescence and the SASP via their ligand‐mediated signalling and can be important SASP regulators in tumour microenvironment as discussed in detail below." (PMID 35674109, 2022). "We hypothesise that since TLR2-activated oesophageal cells produce chemokines, which promote leukocyte trafficking to the tumour microenvironment, they also induce tumour progression via macrophage differentiation." (PMID 33922955, 2021). "These functions were related to several upregulated anti-apoptotic genes and cell cycle progression/proliferation genes, as well as decreased expression of tumor suppressor genes, first identified in mouse models and verified in human samples that expressed high levels of TLR2." (PMID 35048056, 2021). "We demonstrate that TLR2 blockade reduces the effects of tumour-secreted HMGB1 on macrophages." (PMID 33922955, 2021). "TLR2 plays both anti- and pro-tumor roles depending on its expression on immune cells or tumors." (PMID 33898309, 2021). "Similarly, Heat-shock protein 60 signals through TLR2 on tumor cells and promotes lung metastasis in mice." (PMID 34032639, 2021). "Both are also known to activate TLR2, leading us to speculate that these bacteria might directly contribute to immune evasion in tumor cells expressing TLR2 during oral carcinogenesis." (PMID 34638266, 2021).
tumor (continued). "The results showed that unmatched tumor antigen rlipo-OVA-MoGM therapy had no impact on TC-1 tumor growth in either treated tumors or distal tumors, indicating that the antitumor efficacy induced by the combination of the TLR2 agonist and GM-CSF was tumor antigen dependent." (PMID 34599024, 2021). "In the orthotopic 4T1 mouse model, intratumoral administration of SFV/IFNg virus particles alone or in combination with the Pam3CSK4 TLR2/1 ligand led to significant inhibition of tumor growth compared to the administration of the control SFV/Luc virus particles." (PMID 34835178, 2021). "The possibility that TLR2 may facilitate immunosuppression in tumor cells is also of particular interest due to the clinical advancement of TLR2-based treatments for cancer." (PMID 34638266, 2021). "Interestingly, TLR2 agonists are also thought to suppress tumor growth by acting directly on T cells to stimulate an immune response, and these have also been advanced to clinical trials." (PMID 34638266, 2021). "This is yet another example of TLR2 role in tumor-related immunosuppression." (PMID 35048056, 2021). "Thus, it appears that immunosuppression in PDAC tumors is established by bacteria via TLR2 and TLR5 signaling in tumor-associated macrophages." (PMID 34604233, 2021). "Additionally, dimethyl amiloride decreased exosome production by tumor cells and enhanced the antitumor efficacy of the chemotherapeutic drug cyclophosphamide in three different mouse tumor models through TLR2-dependent pathways." (PMID 34337063, 2021). "Mmp2 overexpression in tumor cells is therefore likely to impact other pathways beyond Tlr2/4 signaling that contribute to tumor growth — e.g., degradation of ECM proteins to modify the TME architecture or degradation of IFNAR1 in immune cells (APCs or other cell types) as we previously showed." (PMID 34032639, 2021). "Moreover, another finding indicated that Hsp72 located on the tumor exosomes surface can engage TLR2 expressed on MDSCs." (PMID 34659412, 2021). "Moreover, DCA can increase TLR2 expression in HSCs together with increased TLR2 agonist lipoteichoic acid, which results in the tumor-promoting SASP." (PMID 34957088, 2021). "Activation of TLR1/2 heterodimers and TLR2/6 heterodimers in GAMs plays an important role in extracellular matrix remodeling and tumor expansion through induction of matrix metalloproteinases (MMPs), interleukin (IL)-6, and inducible nitric oxide synthase (iNOS)." (PMID 34715891, 2021). "Lipoteichoic acid is a bacterial component of the intestine which, as a ligand of TLR2, contributes to the development of HCC in obese mice by increasing tumor-promoting senescence-associated secretory phenotype (SASP) of hepatic stellate cells (HSCs) and COX2 expression." (PMID 34957088, 2021). "Interestingly, genes with opposite regulation and over-expressed in tumor stroma are enriched for cytokine secretion and Toll-like receptor 2 signaling." (PMID 34282769, 2021). "On the basis of the encouraging efficacy and specificity shown, our study suggests that the combination of TLR2 agonists and GM-CSF is an excellent combinatorial adjuvant for triggering antitumor immunity and provides preclinical evidence of established tumor regression." (PMID 34599024, 2021). "To determine whether Tlr2 and Tlr4 signaling is required for tumor progression, we monitored tumor incidence and growth up to 19 days following B16 F1 injection in WT, Tlr2–/–, Tlr4–/–, and DKO mice." (PMID 34032639, 2021). "Moreover, tumor progression due to intracellular presence of P. gingivalis under hypoxic conditions has been demonstrated to be independent from TLR2 signaling." (PMID 34298645, 2021). "Moreover, this antitumor effect induced by the dual adjuvants TLR2 agonists and GM-CSF is tumor antigen dependent." (PMID 34599024, 2021). "TLR2 is upregulated on epithelial cells in many tumor types and may support tumor growth in this context." (PMID 34638266, 2021).
tumor (continued). "Blockage of the Bgn-TLR2 or Bgn-TLR4 interaction in E0771 cells by neutralizing antibodies significantly decreased Tnf mRNA expression in E0771 cells stimulated with recombinant biglycan, suggesting that biglycan regulates TNF-ɑ expression in tumor cells through binding to TLR2 and TLR4." (PMID 33966638, 2021). "Furthermore, the expression of Tlr2 and Tlr4 in both hematopoietic and stromal compartments appears to support Mmp2-driven tumor growth." (PMID 34032639, 2021). "To further explore whether i.t. administration of the TLR2 agonist and GM-CSF-containing fusion proteins would lead to a systemic antitumor response, we used a bilateral tumor approach." (PMID 34599024, 2021). "P. gingivalis LPS may stimulate host response via TLRs, like TLR4 and TLR2 that may prevent apoptosis and enhance tumor proliferation; it therefore cooperates in the protection of tumor cells and the progression of cancer." (PMID 33663382, 2021). "The engagement of TLR2 on MC has shown to stimulate tumor growth, and blocking this pathway may be promising in designing of immunotherapeutic strategies." (PMID 31256327, 2020). "However, in some cases, TLR2 activation can lead to an immunosuppressive effect that favors tumor progression." (PMID 33321934, 2020). "It was shown that TLR2-activated APCs can promote effector cells to attack tumor cells." (PMID 33469538, 2020). "The same group of researchers subsequently demonstrated that TLR2 activation may promote the immunosuppressive activity of monocytic-MDSCs, inducing their differentiation into tumor-promoting macrophages." (PMID 33321934, 2020). "The activation of TLR2 on tumor infiltrating myeloid or Treg cells is induced directly by cancer cells, which are able to secrete TLR2 endogenous ligands, such as the chondroitin sulfate proteoglycan versican, HMGB1 (which will be discussed in the following paragraphs) and Wnt5a." (PMID 33321934, 2020). "As discussed in the previous paragraph, TLR2 plays an important role in the activation of innate immune cells and may promote anti-tumor responses in virtue of its ability to activate antigen presenting cells and, consequently, tumor-specific T lymphocytes." (PMID 33321934, 2020). "Of note, TLR2 blocking antibodies exert a double role by acting not only on cancer cells but also on host immune cells, reversing the tumor cell-induced immunosuppressive microenvironment and restoring the activity of anti-cancer cells such as cytotoxic T cells and M1 macrophages." (PMID 33321934, 2020). "Furthermore, TLR2 activation stimulates MDSCs to produce IL-10, which induces macrophage polarization toward the M2 tumor-promoting phenotype, while MDSC-produced IL-6 promotes tumor metastatic growth." (PMID 33321934, 2020). "Therefore, TLR2 activation increases MDSC accumulation in the tumor microenvironment and in lymphoid organs." (PMID 33321934, 2020). "Although, physiologically, the role of DAMP-induced TLR signaling is to activate a pro-inflammatory immune response in order to induce tissue regeneration, their binding to TLR2 and other receptors on tumor cells may promote cancer progression." (PMID 33321934, 2020). "One of the DAMPs that can stimulate TLR2 activation in the tumor milieu is HMGB1." (PMID 33321934, 2020). "However, knocking out the TLR2 gene reduced the shortening of colorectal length, the number of tumors, and the total tumor volume and inhibited the growth of CAC." (PMID 32256204, 2020). "Hsp72 of TEXs from various tumor cells, including lung cancer, could restrain tumor immune surveillance by activating the MDSCs’ immunosuppressive activity by triggering the TLR2 signaling pathway." (PMID 32983146, 2020). "In that case, TLR2 may have a dual role and be a central element in the anti-tumor immune response or in the pro-tumorigenic processes." (PMID 33321934, 2020). "TLR2 seems to play a role also in NK cell-mediated anti-tumor immunity." (PMID 33321934, 2020).
tumor (continued). "However, two papers demonstrated that TLR2 also contributes to tumor angiogenesis in a VEGF-independent manner." (PMID 33321934, 2020). "Knocking out the TLR2 gene also reduced the pathological score and tumor severity." (PMID 32256204, 2020). "High levels of TLR2 expression in tumor tissues of CRC patients have been reported." (PMID 32256204, 2020). "On the other hand, it was shown in an orthotopic B16.F10 melanoma model that TLR2-activated MC could also inhibit tumor growth by an IL-6-dependent mechanism." (PMID 31256327, 2020). "Since the characterization of the role exerted by TLR2 on immunosuppressive cell populations may provide therapeutic tools for the treatment of both autoimmune and neoplastic diseases, many researchers have investigated the effects of TLR2 signaling in MDSCs." (PMID 33321934, 2020). "However, in neoplastic tissues, HMGB1 is actively secreted by inflammatory cells or tumor cells or passively released by dead cells, and it can activate its cognate receptors, including TLR2." (PMID 33321934, 2020). "Of note, TLR2 activation promotes their immunosuppressive function, thus favoring tumor growth." (PMID 33321934, 2020). "This study demonstrates that TLR2 plays a common role in tumor proliferation in CAC and sCRC." (PMID 32256204, 2020). "Increased TLR2 expression has been observed in various cancers, suggesting that TLR2 may play important roles in tumorigenesis and tumor progression." (PMID 30196472, 2019). "Here, we have revealed a TRAPs-mediated regulatory mechanism of CD4+ T cells differentiation whereby HSP90α on the surface of TRAPs educate CD4+ T cells via a TLR2–autocrine IL-6 cascade to express IL-10 and IL-21 and engender immune suppression to promote tumor growth and metastasis." (PMID 31300052, 2019). "Increasing data proposes that the initiation of TLR2/TLR4 signaling enhances tumor cell growth, downregulates apoptosis, and upregulates the synthesis of growth factors and inflammation-associated cytokines by tumor and stromal cells." (PMID 31068944, 2019). "It was found that activating TLR2 promotes tumor metastasis." (PMID 30196472, 2019). "Tumor volume in MIP-treated TLR2−/− mice were comparable with those in PBS-treated control animals." (PMID 31590685, 2019). "However, in a metastatic Lewis lung carcinoma mouse model, CpG ODNs and an anti-TLR2 antibody regimen eradicated synergistic immunosuppressive tissues from the tumor environment." (PMID 31508424, 2019). "The silkworm peptide could play role in inhibiting tumor growth, and it may be related to TLR2‐induced MyD88‐dependent pathway in vitro." (PMID 31024698, 2019). "In gastric cancer TLR2 expression in tumor cells was shown in > 50% patients." (PMID 30976817, 2019). "Expression of TLR2 was increased in circulating tumor cell-positive patients." (PMID 30728901, 2019). "Upon TLR2 stimulation, macrophages in tumors activated, and promote tumor progression and invasion." (PMID 31019508, 2019). "Importantly, versican derived from tumor ECM activates DCs' TLR2, resulting in the production of immunosuppressive IL-10 and DC dysfunction." (PMID 31068944, 2019). "In a GBM model, EDN, a ligand of toll-like receptor-2 (TLR2) that can induce immune cells to infiltrate tumor tissue and inhibit tumor growth, may be favorable for inhibiting GBM cells." (PMID 31805879, 2019). "In addition, TLR2/MyD88 signaling is essential for both tumor cell stemness and gastric tumorigenesis being activated by the inflammatory microenvironment, as was proven by studies involving mouse models." (PMID 30863783, 2019). "For example, TLR2-mediated mast cell activation reduced tumor growth in several mouse models." (PMID 31167464, 2019). "Thus, it has been intriguing what happens in tumor-loading mice when they are treated with EGT together with TAA + TLR2 adjuvant." (PMID 31019508, 2019).